HMGN1P3 (high mobility group nucleosome binding domain 1 pseudogene 3)
Gene: Processed pseudogene on chromosome 14 (68,887,785 to 68,888,084, reverse strand). Ensembl gene ENSG00000258967.
Diseases named in the same sentence as HMGN1P3 in open-access papers:
HMGN1P3 is named in the same sentence as 1 disease in open-access papers, as found by Europe PMC text mining. Sharing a sentence is not in itself a finding about the gene and the disease.
HMGN1P3 shares sentences with these, for which no sentence is quoted: cancer (1 paper).